UCP1 (uncoupling protein 1)
Diseases named in the same sentence as UCP1 in open-access papers (continued):
Sharing a sentence is not in itself a finding about the gene and the disease.
Obesity (continued). "Oral supplementation could affect the signals associated with lipid catabolism, lipolysis, mitochondria biogenesis, and uncoupling protein 1 (UCP1)-positive cells in the adipose tissues and contribute to managing obesity and metabolic syndrome." (PMID 35268752, 2022). "Taken together, these results indicated that hASCs suppressed obesity by increasing UCP-1 expression and enhancing energy expenditure, and this effect might be due to the increased M2 macrophages." (PMID 34222665, 2021). "The expression of UCP1 in brown WAT could resist obesity and metabolic dysfunction by dissipating chemical energy as heat." (PMID 34064117, 2021). "However, obesity induced by HFD feeding is also known to induce Ucp1 expression in iBAT, and our finding confirms a similar increase in scBAT in mice housed at ambient temperature." (PMID 34199472, 2021). "UCP1 deficiency exacerbates dietary obesity-induced endothelial dysfunction, vascular inflammation, and atherogenesis in mice, which was not rectified by reconstitution of UCP1 in interscapular brown adipose tissue." (PMID 34878840, 2021). "In light of these findings, we wondered whether UCP1 KI pigs could be utilized to explore the regulatory mechanism of lipid metabolism in insulin resistance and obesity in humans." (PMID 35096834, 2021). "Interestingly, FGF21-mediated iWAT browning appeared to protect UCP1 KO mice housed at room temperature from diet-induced obesity." (PMID 34192547, 2021). "Interestingly, treatment with melatonin, which has been described has having an anti-obesity effect, was able to restore not only UCP1 expression but also its functionality in obese rats." (PMID 34829617, 2021). "Because UCP1 dissipates energy substrates such as glucose and fatty acids to produce heat, the promotion of brown adipogenesis also contributes to the prevention of obesity." (PMID 33525404, 2021). "However, when Treg-specific IL-10 was knocked down, the expression of uncoupled protein 1 (UCP1) and other thermogenic genes in adipocytes in white AT was increased, protecting mice from insulin resistance and diet-induced obesity." (PMID 34515616, 2021). "In a thermoneutral environment, UCP1 KO mice develop HF diet-induced obesity." (PMID 34829779, 2021). "Moreover, genetic ablation of either BAT or uncoupling protein 1 (UCP1), the protein responsible for the thermogenic process in BAT, predisposes mice to obesity." (PMID 33676029, 2021). "Maternal RYGB prevented obesity in offspring, probably by increasing the expression of UCP1." (PMID 33441773, 2021). "In addition, the activation of PPARα by chronic fenofibrate administration increases the gene expression of PGC1α and irisin, and it yields UCP-1-positive beige cells in the sWAT of the mice with HFD-induced obesity." (PMID 34445679, 2021). "Therefore, it has been assured that the increased UCP1 expression in WAT is a potential molecular strategy to conquer obesity." (PMID 33959308, 2021). "Dysfunctional BAT in obese subjects could reduce EE and contribute to weight gain, as observed in mice with selective disruption of Ucp1 that develop obesity when housed at thermoneutral conditions." (PMID 33729178, 2021). "HFD-induced obesity reduced the level of UCP1 and the mass of BAT, as well as the expression of genes related to glucose and lipid metabolism; increased the expression of genes related to inflammatory reactions; and caused the blood glucose and lipid levels to rise." (PMID 34082784, 2021). "However, Ucp1−/− mice housed below thermoneutrality have resistance to diet-induced obesity due to decreased metabolic efficiency, highlighting that dysfunctional BAT does not necessarily cause weight gain and is dependent on the environmental conditions." (PMID 33729178, 2021). "For example, GC-induced obesity develops to the same extent in WT and UCP1 KO models." (PMID 34445209, 2021).
Obesity (continued). "While often praised for its potential benefits in metabolic diseases such as obesity or diabetes, browning and the activation of uncoupling protein 1 (UCP‐1) in hypermetabolic conditions such as in burns and cancer cachexia appear to be detrimental and exhaust body mass reserves." (PMID 34185433, 2021). "It has been proposed that irisin mediates the beneficial effects of exercise on metabolism by upregulation of uncoupling protein 1 (UCP1) expression and the subsequent elevation of energy expenditure, resulting in the amelioration of obesity-induced insulin resistance." (PMID 33672565, 2021). "Revealing the involved signal pathway and transcription regulation of Ucp1 in BAT’s energy metabolic process not only helps us to better understand the important role of Ucp1 in BAT energy metabolism control but also provides a theoretical foundation for obesity treatment based on BAT." (PMID 34943089, 2021). "It is noticed that deficiency of UCP1, which is primarily thought to be necessary, or inability of adipose fatty acid oxidation in mice did not cause an obvious trend of obesity at thermoneutrality, suggesting that there are alternative thermogenic mechanisms." (PMID 34367068, 2021). "Notably, the mouse model has been used to reveal mechanisms controlling UCP1 synthesis, thermogenesis, and possible implications for human obesity." (PMID 33634052, 2020). "Commiphora myrrha extract normalized serum leptin levels through different possible pathways such as increasing UCP1 expression in brown adipose tissue, which subsequently increased energy expenditure and reduced obesity development which reduced leptin synthesis and secretion by adipocytes." (PMID 32197395, 2020). "Obesity also decreased the abundance of UCP1, whereas exercise training resulted in an increase." (PMID 32230849, 2020). "It is of high clinical importance to determine the regulator of UCP1-independent thermogenesis because understanding the mechanism may lead to the development of new treatments for obesity and type 2 diabetes." (PMID 32849287, 2020). "Thus, depletion of ERK3 inhibits lipolysis by reducing FOXO1-mediated ATGL expression but at the same time promoting Ucp1 expression and energy dissipation by brown as well as white adipose tissue, thereby protecting against obesity and diabetes." (PMID 32139423, 2020). "The mitochondria of brown fat cells express specific UCP1, which may have an anti-obesity effect because it can oxidize and decompose fat30." (PMID 33004990, 2020). "However, TUDCA treatment of DBP exposed mice returned these parameters nearly to the levels of the controls, with increased expression of UCP1, lower expression of Bip and Chop and ameliorated obesity." (PMID 33004990, 2020). "Brown adipose tissue (BAT) possessed the anti-obesity potential, which was characterized by large numbers of mitochondria, where uncoupling protein 1 (UCP1) possesses the ability to utilize free fatty acids and glucose for heat generation (non-shivering thermogenesis)." (PMID 32321934, 2020). "Therefore, the increase of beige adipocytes is marked by increases of PGC-1α and UCP-1 and results in increased energy expenditure that can then counter obesity." (PMID 33425000, 2020). "A number of obesity-associated genes have been identified in adipogenesis regulation, such as melanocortin-4 receptor (MC4R), uncoupling protein-1 (UCP1), and pro-opiomelanocortin (POMC)." (PMID 33425901, 2020). "Given the importance of therapeutically treating the obesity epidemic, the underlying mechanisms of energy loss in the presence and absence of UCP1 are indisputably important." (PMID 32005798, 2020). "We postulate that increased expression of Ucp1 in mice deficient for ERK3 in adipocytes fed ad libitum with HFD at least partially contributes to the enhanced energy expenditure observed in these animals, which in turn protects from HFD-induced obesity." (PMID 32139423, 2020).
Obesity (continued). "Insulin-like growth factor 2 mRNA-binding protein 2/IGF-II mRNA-binding protein 2- (IGF2BP2/IMP2-) deficient mice have a higher level of the uncoupling protein 1 (UCP1) polypeptide in brown fat, contributing to the higher energy expenditure and resistance to diet-induced obesity." (PMID 33532487, 2020). "It was reported that mitochondrial dysfunction-induced impairing oxidative capacity in brown adipocytes even without any change in UCP1 level is strongly linked to diet-induced obesity." (PMID 32595696, 2020). "Some of these appear to be regulated by the loss of UCP1, but none associates to obesity resistance, as their regulation was not differentially affected in dKO mice." (PMID 32005798, 2020). "Collectively, our results show that knockout of Ahr mediated by Pdgfrα-Cre is protective against diet-induced obesity and suggest a mechanism by which enhanced UCP1 activity within BAT might confer these effects." (PMID 32730300, 2020). "The generation of UCP1/FGF21 double-knockout mice (dKO) fully reverses obesity resistance." (PMID 32005798, 2020). "Extending support to this thought, obesity-prone C57/BL6 and obesity-resistant SV129 mice have differential expression of UCP-1 level in subcutaneous fat, which could mediate obesity resistance." (PMID 32466447, 2020). "UCP1, in fact, represents the hallmark of brown adipose tissue (BAT) and is a reliable marker of browning of white adipose tissue (WAT), which has been shown to protect from obesity and type 2 diabetes." (PMID 33376578, 2020). "Brown adipose tissue helps moderate energy balance inside the body through non-shivering thermogenesis, maintain basal body temperature, and may mitigate obesity through the production of heat, attributed to the expression of uncoupling protein 1 gene (UCP-1)." (PMID 32595696, 2020). "Therefore, our findings, in two distinct mouse models as suggested support the conclusions that mast cell Tph1 protects against obesity induced insulin resistance by enhancing adipose tissue Ucp1 and whole body energy expenditure." (PMID 31974364, 2020). "UCP1-independent energy releasing processes were recently described in adipocytes, which may provide an alternative way to reduce obesity." (PMID 32316277, 2020). "Accordingly, Ucp1 induction is thought to induce energy expenditure and may be useful in strategies to prevent obesity and its related metabolic diseases." (PMID 32443555, 2020). "The lean phenotype observed in Ucp1−/- mice was likely due to a compensatory increase in skeletal muscle shivering to generate heat in the absence of BAT-mediated thermogenesis, as later studies showed that UCP1 deletion promoted obesity when mice were housed at thermoneutral temperatures." (PMID 32713230, 2020). "Elevated expression of Ucp1 in different adipose tissue depots drives energy dissipation of adipocytes, which can increase the energy expenditure of the entire organism and prevent the development of obesity." (PMID 32139423, 2020). "Specifically, screening potential UCP1 activators with the method of CMAP, which further enhance BAT activity and induce browning of WAT, could be a feasible therapeutic strategy for obesity and associated diseases." (PMID 32190098, 2020). "Thus, Cnot7- or Tob-KO mice are resistant to HFD-induced obesity with increased Ucp1 mRNA level in iWAT and BAT." (PMID 33634052, 2020). "In this sense, some nucleotide substitutions in the UCP1 gene were described in obese people suggesting that specific variations of UCP1 could promote energy storage and contribute to the development of obesity." (PMID 32069871, 2020). "Herein, we hypothesize that obesity-induced expression/activation of ASK1 in adipocytes negatively affects UCP1 protein expression in WAT thereby mediating an inhibitory effect on adipose tissue browning." (PMID 32242025, 2020). "Similar to Emr1, higher levels of Entpd1, Cd38, and Nt5e were found in BAT of ob/ob mice, while no obesity-associated changes in Ucp1 expression were detected." (PMID 33025427, 2020).
Obesity (continued). "UCP1 is an important gene that controls the development of obesity and DM2." (PMID 32197395, 2020). "Even in 129S2/sv mice, UCP1 ablation leads to increased obesity and higher metabolic efficiency." (PMID 30807213, 2019). "Similarly, the UCP1 levels in ingWAT of mice living at room temperature are actually reduced by a high-fat diet in both obesity-prone (AKR) and obesity-resistant (SWR) strains." (PMID 30807213, 2019). "In addition, high expression of FMO3 is also associated with obesity, and FMO3 knockdown or genetic deletion showed a higher positivity of UCP1 in WAT." (PMID 31262098, 2019). "Suppression of obesity observed in H. polygyrus-infected obese mice was attenuated in the presence of reserpine, indicating the involvement of neurogenic NE in the expression of UCP1 and the suppression of weight gain." (PMID 30962398, 2019). "Many studies have demonstrated that quercetin supplementation prevents HFD-induced obesity and metabolic syndrome and increases the expression of UCP1 and thus thermogenesis through the adenosine monophosphate-activated protein kinase (AMPK) signalling pathway." (PMID 31346342, 2019). "This discrepancy suggests a diet‐dependent anti‐obesity effect of succinate, which may be attribute to different baseline UCP1 activation in chow and HFD condition." (PMID 31318145, 2019). "Indeed, PG extract increased thermogenic gene expression (such as SIRT1, PPARα, UCP1, PGC1α), thereby inducing the browning of white adipose tissue, resulting in an anti-obesity effect." (PMID 31615016, 2019). "RictorMyf5-Cre ablation in BAT causes higher mitochondrial activity and protects mice from high-fat diet-induced obesity and hepatic steatosis at thermoneutrality, while in acute cold challenge, RictorMyf5-Cre mice show significantly induced Ucp1 expression in BAT." (PMID 31708995, 2019). "The loss of function of Ucp1 in mice accelerates the development of obesity in response to a high-fat diet, while the overexpression of Ucp1 in WAT results in protection against diet-induced obesity in mouse models." (PMID 31312229, 2019). "Whereas this initially may be considered paradoxical, given that UCP1 is supposed to counteract obesity, such a recruitment of the tissue is fully in agreement with a homeostatic role of the tissue." (PMID 30807213, 2019). "Indeed, UCP1 ablation does augment diet-induced obesity, at least when mice are housed at thermoneutrality." (PMID 30807213, 2019). "Therefore, we have examined to which degree UCP1 ablation has similar metabolic effects in a mouse strain known to be obesity resistant: the 129S strain." (PMID 30807213, 2019). "We found that CA promotes activation of BAT function and differentiation by upregulation of genes related to BAT thermogenesis, mitochondrial biogenesis and mitochondrial activation such as Pgc1a, Ucp1, Prdm16, Sirt3, Cidea and CytC, thereby suppress obesity by promoting EE." (PMID 31443565, 2019). "Res known as a natural polyphenol that has anti-obesity effect due to activation of UCP-1." (PMID 31640715, 2019). "In a rat model of HFD-induced obesity, propanthocyanidin supplementation inhibited the weight gain induced by a high-fat diet, increased the activity of cytochrome c oxidase activity, and enhanced UCP1 expression in brown adipocytes." (PMID 31346342, 2019). "In vitro studies have found that SIRT3-deficient brown adipocytes had reduced UCP-1 expression and mitochondrial biogenesis, while a HS diet-induced decrease in SIRT3 impaired mitochondrial biogenesis in BAT, which was correlated with obesity." (PMID 31409767, 2019). "Obesity-induced increases in BAT UCP1 may serve as a means to restore energy balance during energy surplus." (PMID 30804793, 2019). "Moreover, we showed that VAT of patients with obesity expresses more UCP1 than SAT, incrementing with increase of BMI (BMI > 50 kg/m2)." (PMID 31440209, 2019).
Obesity (continued). "Blocking interactions of NE with its receptor on adipocytes resulted in the failure to prevent weight gain and to enhance UCP1 expression in obese mice infected with H. polygyrus, indicating that NE is responsible for the protective effects of H. polygyrus on obesity." (PMID 30962398, 2019). "A corresponding question is whether UCP1 is the only mediator of diet-induced thermogenesis or whether other mechanisms are present in other less obesity-prone strains." (PMID 30807213, 2019). "Thus, it was concluded that PE has an anti-obesity effect by controlling lipid metabolism through PPARγ and UCP1." (PMID 31137922, 2019). "Thus, the protective role of H. polygyrus infection against obesity is dependent on NE, presumably by inducing UCP1 for energy expenditure in adipocytes." (PMID 30962398, 2019). "UCP1 plays important roles in the maintenance of energy homeostasis and protection against obesity." (PMID 31312229, 2019). "We previously observed that ovariectomy-induced obesity also increases BAT UCP1." (PMID 30804793, 2019). "Remarkably, UCP1-KO mice are resistant to diet-induced obesity at sub-thermoneutral temperatures, presumably via activation of poorly defined alternate routes of energy loss in the absence of UCP1." (PMID 31614705, 2019). "We also think that the decisive effector that prevents obesity is increased UCP1 expression." (PMID 30962398, 2019). "However, it is surprising that such a moderate activating effect of Capsiate was sufficient to inhibit HFD-induced obesity in mice, enhance energy expenditure and increase UCP-1 mRNA." (PMID 30518154, 2018). "Increasing the protein:carbohydrate ratio in high fat diets attenuate obesity development and increase UCP1 expression in mice kept at both 22°C and at thermoneutrality, but obesity development and feed-efficiency in mice kept at the two different temperatures have not yet been directly compared." (PMID 30631281, 2018). "Attenuated obesity corresponded with marked upregulation of uncoupling protein 1 (UCP1), a key protein involved in energy expenditure, in adipose tissue, suppression of glucose and triglyceride levels, and alteration in the expression of key genes involved in lipid metabolism." (PMID 29545532, 2018). "Mitochondria in BAT are signed with the high level of uncoupling protein 1 (UCP1), which could uncouple respiration and dissipates chemical energy as heat to prevent obesity." (PMID 30258363, 2018). "To assess the hypothesis that UCP1 gene expression is inhibited by inflammation in obesity, we measured ITGA4 gene expression before and after the intervention." (PMID 30618796, 2018). "Interestingly, after the exercise intervention, UCP1 mRNA increased in individuals with obesity (∼1.65 fold), reaching levels comparable to those of Nw group." (PMID 30618796, 2018). "In addition, a study found that young and mature animals, as well as obesity prone Osborne–Mendel rats, on a MR diet exhibited long-term increases in energy expenditure and uncoupling protein-1 (UCP-1) in both brown and white adipose tissue." (PMID 29780356, 2018). "However, brown fat mass and its Ucp1 expression were drastically reduced in these mice, indicating that the resistance to obesity was largely due to the increased adaptive thermogenesis in WAT but not in BAT." (PMID 28677104, 2018). "Here, we have shown that low-grade inflammation could be a potential mechanism behind reduced UCP1 expression, which could ultimately lead to obesity or worsen the consequences of obesity." (PMID 28481291, 2017). "Recent studies on energy intake and reproductive output reported that UCP1 participates in a specific biological process, namely, thermogenic respiration in adipose tissue, negatively regulating fat accumulation because of the potential contribution of UCP1 to obesity." (PMID 29258237, 2017). "Interestingly, deletion of Akt1 in DJ-1 transgenic mice can rescue DJ-1 overexpression-induced Ucp1 inhibition and obesity." (PMID 28224045, 2017).